MFSD12 (major facilitator superfamily domain containing 12)
Description:
Transporter that mediates the import of cysteine into melanosomes, thereby regulating skin pigmentation. In melanosomes, cysteine import is required both for normal levels of cystine, the oxidized dimer of cysteine, and provide cysteine for the production of the cysteinyldopas used in pheomelanin synthesis, thereby regulating skin pigmentation. Also catalyzes import of cysteine into lysosomes in non-pigmented cells, regulating lysosomal cystine and cysteine storage, which is essential for redox homeostasis.
Synonyms: C19orf28; MGC20700; PP3501; SLC59B1
Tractability: Antibody: UniProt predicts a signal peptide or a membrane-spanning region; its Gene Ontology location is reachable by antibodies, with medium confidence. PROTAC: its protein half-life has been measured.
Gene: Protein-coding gene on chromosome 19 (3,538,261 to 3,574,290, reverse strand). Ensembl gene ENSG00000161091.
Subcellular location: Melanosome membrane; Lysosome membrane
Gene Ontology:
Molecular function: cysteine transmembrane transporter activity; symporter activity
Biological process: cysteine transmembrane transport; pigment metabolic process involved in pigmentation; regulation of melanin biosynthetic process; carbohydrate transport; negative regulation of melanin biosynthetic process
Cellular component: late endosome; lysosomal membrane; lysosome; melanosome; melanosome membrane; plasma membrane; membrane
Genetic constraint (gnomAD): Loss-of-function variants: 69 observed, 46.45 expected, observed/expected ratio (o/e) 1.49, 90% interval 1.22 to 1.8. The synonymous counts are far from expectation, so gnomAD's model fits this gene poorly and the ratio says little. Missense variants: 921 observed, 626.11 expected, observed/expected ratio (o/e) 1.47, 90% interval 1.39 to 1.55. Synonymous variants: 441 observed, 284.37 expected, observed/expected ratio (o/e) 1.55, 90% interval 1.43 to 1.68.
Homologues: Orthologues: chimpanzee MFSD12 (98% identical), pig MFSD12 (89% identical), mouse Mfsd12 (85% identical), rat Mfsd12 (83% identical), dog MFSD12 (80% identical), guinea pig MFSD12 (77% identical), tropical clawed frog mfsd12 (63% identical), zebrafish mfsd12a (62% identical), macaque MFSD12 (54% identical), Caenorhabditis elegans mfsd-12 (39% identical). Paralogues in human: MFSD2A (20% identical), MFSD2B (20% identical).
Diseases named in the same sentence as MFSD12 in open-access papers:
MFSD12 is named in the same sentence as 16 diseases in open-access papers, as found by Europe PMC text mining. Sharing a sentence is not in itself a finding about the gene and the disease. The quoted sentences say what the papers report.
melanoma (7 papers, 2019 to 2025). A malignant, usually aggressive tumor composed of atypical, neoplastic melanocytes. "Studies have demonstrated that MFSD12 plays a crucial role in various cancers, particularly in the growth and progression of tumors including melanoma, breast cancer, and lung cancer." (PMID 41194934, 2025). "In melanoma, elevated MFSD12 expression correlates with enhanced cell proliferation and accelerated tumor growth by promoting cell cycle progression." (PMID 41194934, 2025). "It was discovered that melanoma had a markedly and specifically raised expression of MFSD12, and that this protein stimulated cell cycle progression, therefore leading to increased cell proliferation." (PMID 38903991, 2024). "MFSD12, involved in the import of cysteine into melanosomes and lysosomes, has been reported to enhance melanoma cell proliferation." (PMID 38654325, 2024). "Current studies suggest that MFSD12 has a positive complex role in the growth and progression of tumors such as melanoma, breast cancer, and lung cancer." (PMID 38903991, 2024). "In vivo studies additionally verified that MFSD12 interference prevents lung metastasis of melanoma." (PMID 38903991, 2024). "Clinical research revealed a favorable correlation between reduced overall survival (OS) and disease-free survival (DFS) in melanoma patients and high expression of MFSD12." (PMID 38903991, 2024). "Increased expression of MFSD12 leads to proliferation of melanoma cells, suggesting that MFSD12 is a useful prognostic biomarker and a potential therapeutic target for melanoma." (PMID 38903991, 2024). "MFSD12 was significantly upregulated in melanoma tissues, with interreference in its expression in A2058 and M14 melanoma cells found to significantly suppress tumor cell proliferation." (PMID 35747825, 2022). "Bioinformatic analysis revealed that upregulated expression of MFSD12 is a key promoter of cell proliferation, potential prognostic biomarker, and therapeutic target for melanoma." (PMID 34386038, 2021). "We further determined the molecular mechanism of MFSD12 in melanoma according to the GO and KEGG analyses." (PMID 30385854, 2019). "Expression of FAM174B, MAD1L1, SCARB1, MFSD12, SEMA6A, SLC45A2, and TBC1D16 was found to be upregulated and associated with worse OS in melanoma patients, while only MFSD12 and SLC45A2 were associated with worse DFS for melanoma patients." (PMID 30385854, 2019). "Through quantification analysis using Image-Pro Plus Chen Y .0, the expression of MFSD12 was found to be noticeably upregulated in melanoma tissues compared with the benign nevus sections (p < 0.001)." (PMID 30385854, 2019). "The expression level and role of MFSD12 in melanoma were evaluated, and the correlation between MFSD12 and the major pathological parameters of melanoma was investigated." (PMID 30385854, 2019). "Coincidentally, the MFSD12 mRNA was found to be increased in 23/30 melanoma tissues compared with peritumoral normal tissues (p = 0.002)." (PMID 30385854, 2019). "We further employed subcutaneous xenograft tumor models to identify the role and therapeutic implication of MFSD12 in melanoma." (PMID 30385854, 2019). "Clinically, high MFSD12 expression was positively associated with shorter overall survival (OS) and disease-free survival (DFS) in melanoma patients, and MFSD12 was an independent prognostic factor for OS and DFS in melanoma patients." (PMID 30385854, 2019). "The expression of MFSD12 was significantly upregulated in melanoma tissues compared with normal tissues, and the upregulation in melanoma is very conspicuous compared with that in other kinds of cancer." (PMID 30385854, 2019). "High level of MFSD12 is a poor prognostic factor for melanoma patients and can serve as a potential therapeutical target of melanoma." (PMID 30385854, 2019). "In conclusion, elevated MFSD12 expression promotes melanoma cell proliferation, and MFSD12 is a valuable prognostic biomarker and promising therapeutic target in melanoma." (PMID 30385854, 2019).
melanoma (continued). "A high MFSD12 expression level represented a promising and independent prognostic variable for the prediction of melanoma progression." (PMID 30385854, 2019). "First, the expression of MFSD12 was detected in six melanoma cell lines (A375, A2058, A875, SK-MEL-28, MV3, and M14) and a normal skin cell line (HaCaT) by western blot and qRT-PCR." (PMID 30385854, 2019). "In melanoma, the expression of MFSD12 was noticeably upregulated and the interference of MFSD12 expression in A2058 and M14 melanoma cells markedly decreased cell proliferation." (PMID 30385854, 2019). "Therapeutically, in vivo assays further confirmed that MFSD12 interference inhibited tumor growth and lung metastasis in melanoma." (PMID 30385854, 2019). "In conclusion, the expression of MFSD12 was markedly upregulated in melanoma and the elevated MFSD12 promoted melanoma progression by inducing cell proliferation via the PI3K–AKT pathway." (PMID 30385854, 2019). "Our results indicate that the levels of MFSD12 mRNA and protein are consistently increased in human melanoma tissues." (PMID 30385854, 2019). "MFSD12 mRNA and protein were found to be obviously upregulated in the melanoma cells especially in A2058 and M14 cells compared with the HaCaT cells." (PMID 30385854, 2019). "Among these DEGs, major facilitator superfamily domain-containing 12 (MFSD12) was found to have significantly and specifically upregulated expression in melanoma, and elevated MFSD12 level promoted cell proliferation by promoting cell cycle progression." (PMID 30385854, 2019). "When compared to its role in other malignancies such as melanoma and breast cancer, where MFSD12 primarily drives tumorigenesis through metabolic reprogramming and proliferation, our study unveils a distinctive facet of MFSD12 in LIHC." (PMID 41194934, 2025). "The increased MFSD12 expression promoted melanoma cells’ proliferation, indicating that MFSD12 mRNA may be a new diagnostic target with high sensitivity and specificity." (PMID 35250903, 2021). "By these analyses, we showed that upregulated MFSD12 and SLC45A2, which were associated with OS and DFS, may play an important role in melanoma." (PMID 30385854, 2019). "To examine whether high expression of MFSD12 influences melanoma cell proliferation through the PI3K-AKT pathway, we treated A2058-Vector and M14-Vector cells with LY294002, a PI3K inhibitor (50 μM, 24 h)." (PMID 30385854, 2019). "Importantly, MFSD12 interference significantly weakened the tumor growth and metastasis in vivo, which further highlighted the important role of MFSD12 in melanoma progression." (PMID 30385854, 2019). "Here, the MFSD12 mRNA expression in melanoma tissues was found to be significantly upregulated compared with that in normal tissues and in other cancers, suggesting that MFSD12 mRNA may be a novel diagnostic target with high sensitivity and specificity." (PMID 30385854, 2019). "LY294002 prominently inhibited the proliferation of melanoma cells with a high level of MFSD12." (PMID 30385854, 2019). "Furthermore, we investigated the expression of MFSD12 in a TMA containing 197 melanoma tissue samples." (PMID 30385854, 2019). "In conclusion, MFSD12 is a risk marker for OS and DFS in melanoma patients." (PMID 30385854, 2019). "All of these data indicate that MFSD12 upregulation promotes the proliferation of melanoma cells." (PMID 30385854, 2019). "However, little researches have focused on the expression level and role of MFSD12 in cancers, including melanoma." (PMID 30385854, 2019). "In addition, the prognostic value of MFSD12 in melanoma was analyzed." (PMID 30385854, 2019). "Flow cytometric analysis was then performed and showed that silencing the expression of MFSD12 increased the percentage of cells in G1 phase and decreased the percentage of cells in S phase, which indicated that MFSD12 might promote the G1-to-S phase transition in melanoma cells." (PMID 30385854, 2019).
melanoma (continued). "Previous studies have also shown that major facilitator superfamily domain containing 12 (MFSD12), which is highly expressed in melanoma, induces proliferation of melanoma cells via the PI3K- AKT signaling pathway." (PMID 35747825, 2022). "Therefore, we speculated that MFSD12 may play a key role in melanoma and is of great significance." (PMID 30385854, 2019). "Oddly, both MFSD12 and SLC45A2 belong to the major facilitator superfamily, indicating that MFS may play important roles in melanoma." (PMID 30385854, 2019). "MFSD12 upregulation did not influence melanoma cell metastasis." (PMID 30385854, 2019).
breast carcinoma (4 papers, 2024 to 2025). "Furthermore, in patients with breast cancer, MFSD12 overexpression was linked to unfavorable side effects and a worse prognosis from treatment." (PMID 38903991, 2024). "The MFSD12-T254A mutant inhibits MFSD12 function and suppresses tumor progression, whereas overexpression of MFSD12 worsens the prognosis of breast cancer patients." (PMID 38785550, 2024). "Increased lysosomal stores of cyst(e)ine, which is released by cystinosin (CTNS) to maintain GSH levels and buffer oxidative stress in breast cancer cells, occurs through activation of the major facilitator superfamily domain containing 12 (MFSD12)." (PMID 38785550, 2024). "The findings point to MFSD12 as a possible therapeutic target of breast cancer and highlight the crucial role that lysosomal cysteine storage plays in adaptive redox homeostasis." (PMID 38903991, 2024).
cystinosis (2 papers, 2024 to 2025). Cystinosis is a metabolic disease characterized by an accumulation of cystine inside the lysosomes, causing damage in different organs and tissues, particularly in the kidneys and eyes. "Beyond pigmentation, MFSD12 has been implicated in lysosomal storage disorders, particularly cystinosis." (PMID 41194934, 2025). "Research indicates that MFSD12 loss can decrease lysosomal cystine accumulation, a key pathological feature of cystinosis." (PMID 41194934, 2025). "Further studies found that in individuals with cystinosis, a lysosomal storage disease brought on by the inactivation of the cystine-exporting proteins in lysosomes, deletion of MFSD12 decreased the buildup of cystine in the lysosomes of fibroblasts." (PMID 38903991, 2024). "In experimental cystinosis models, MFSD12 loss reduced cystine accumulation without restoring proximal tubule function." (PMID 41194934, 2025). "Since MFSD12 is crucial to cysteine input by lysosomes and melanosomes, MFSD12 inhibitors may offer a novel class of drugs for the treatment of cystinosis." (PMID 38903991, 2024). "However, despite this reduction, experimental models show no improvement in proximal tubular function, suggesting that while MFSD12 modulates cystine levels, it does not fully ameliorate the functional deficits associated with cystinosis." (PMID 41194934, 2025).
lung carcinoma (2 papers, 2024 to 2025). "In both breast and lung cancers, MFSD12 serves as a key oncogenic promoter, with its overexpression associated with poorer patient prognosis." (PMID 41194934, 2025). "Therefore, MFSD12 is a promising marker of the macrophage subtype and a new predictive biomarker for lung cancer." (PMID 38903991, 2024).
lysosomal storage disease (2 papers, 2024 to 2025). A metabolic disorder caused by mutations in proteins critical for lysosomal function, including lysosomal enzymes, lysosomal integral membrane proteins, and proteins involved in the post-translational modification and trafficking of lysosomal proteins. "Moreover, the potential association between MFSD12 and lysosomal storage disorders may offer insights into novel mechanisms underlying LIHC development, particularly in scenarios where metabolic and storage pathways are compromised." (PMID 41194934, 2025). "As a cysteine transporter, MFSD12 contributes to lysosomal storage disease pathogenesis, suggesting its potential as a therapeutic target for inhibiting tumor progression, preventing metastasis, and improving treatment outcomes." (PMID 41194934, 2025). "This article reviews the molecular mechanisms of MFSD12 in a variety of cancers and lysosomal storage diseases." (PMID 38903991, 2024). "Previous studies have shown that MFSD12 mediates cysteine transport in lysosomes and plays a leading role in the control of lysosomal storage diseases and signaling pathways in a variety of cancers." (PMID 38903991, 2024). "At the same time, as a transporter of cysteine, MFSD12 is also involved in the development of lysosomal storage diseases." (PMID 38903991, 2024). "Beyond its oncogenic functions, MFSD12 plays significant roles in lysosomal storage diseases." (PMID 41194934, 2025).
Alzheimer disease (1 paper, 2026). A progressive, neurodegenerative disease characterized by loss of function and death of nerve cells in several areas of the brain leading to loss of cognitive function such as memory and language. "In replication analyses, 21 genes showed nominal support in UK Biobank and Alzheimer's Disease Genetics Consortium (ADGC) cohorts, with eight genes (TREM2, ACADS, MFSD12, NUP210L, PIEZO2, PSEN1, SMURF2, AKAP13) supported under identical masks." (PMID 41960309, 2026).
cholangiocarcinoma (1 paper, 2025). A carcinoma that arises from the intrahepatic biliary tree (intrahepatic cholangiocarcinoma) or from the junction, or adjacent to the junction, of the right and left hepatic ducts (hilar cholangiocarcinoma). "Within tumor subtypes, MFSD12 expression was notably enriched in LIHC compared to cholangiocarcinoma (CC) and normal controls, suggesting a subtype-specific regulatory mechanism." (PMID 41194934, 2025). "These MFSD12-expressing cells were significantly more abundant in the LIHC tumor core and edge than in nearby normal tissue, blood, or cholangiocarcinoma, indicating subtype-specific upregulation." (PMID 41194934, 2025). "Finally, an examination of MFSD12 expression across immune cell types in normal, cholangiocarcinoma, and LIHC tissues demonstrated that innate lymphoid-normal cells exhibited the highest levels of MFSD12 expression, whereas other normal cells showed lower expression levels." (PMID 41194934, 2025).
hepatocellular carcinoma (1 paper, 2025). A malignant tumor that arises from hepatocytes. "To elucidate the functional role of MFSD12 in the progression of hepatocellular carcinoma, we conducted in vitro experiments utilizing HEP 3B2.1–7 cells subjected to MFSD12 knockdown." (PMID 41194934, 2025).
liver cancer (1 paper, 2025). An epithelial or non-epithelial malignant neoplasm that arises from the liver. "In liver cancer research, while MFSD12’s specific mechanisms remain understudied, its established roles in other cancers suggest potential functions." (PMID 41194934, 2025).
lung adenocarcinoma (1 paper, 2025). A carcinoma that arises from the lung and is characterized by the presence of malignant glandular epithelial cells. "Conversely, in kidney chromophobe (KICH), lung adenocarcinoma (LUAD), lung squamous cell carcinoma (LUSC), and thyroid carcinoma (THCA), MFSD12 expression was lower in cancer tissues than in the corresponding normal tissues." (PMID 41194934, 2025).
Lymphatic Metastasis (1 paper, 2019). Transfer of a neoplasm from its primary site to lymph nodes or to distant parts of the body by way of the lymphatic system. "The univariate analysis showed that Breslow thickness, Clark level, lymphatic metastasis, distant metastasis, and clinical stage, as well as MFSD12 staining, were associated with OS and DFS." (PMID 30385854, 2019).